RUNX2 (RUNX family transcription factor 2)
Diseases named in the same sentence as RUNX2 in open-access papers (continued):
Sharing a sentence is not in itself a finding about the gene and the disease.
cancer (continued). "Additionally, the STRING database shows that COL10A1 closely interacts with several proteins, of which some are famously described as potent promoters of cancer stem cells and mesenchymal transformation, such as MMP13, SOX9, and RUNX2." (PMID 36267978, 2022). "In a variety of cancer cell lines, epigenetic regulators HDAC1 and other HDAC proteins could bind to the RUNX2 P2 promoter to potentiate its transcription." (PMID 36429115, 2022). "Moreover, LEF1, RUNX2, CSF1R, VAV3, and FZD3 have been reported to take part in the development of cancer." (PMID 35340229, 2022). "Three genes (RUNX2, ERG and MMP3) are involved in “transcriptional misregulation in cancer”." (PMID 34830910, 2021). "Moreover, in 1019 cancer cell lines, there were positive correlation between ASPH and RUNX2 or COL1A1." (PMID 33015050, 2020). "Recently, several reports (prevalently microRNA studies) have indicated that the elevated expression of RUNX2 or SOX9 conferred resistance to taxanes (prevalently docetaxel) and CDDP in prostate, gastric, lung, breast, and ovarian cancer cells and tissues." (PMID 33287223, 2020). "The positive rate of Vimentin, VE-cadherin, and Galectin-3 expression in the presence of Runx2 was higher than in cancer cells that did not express Runx2, while the positive rate of E-cadherin in Runx2-positive cells was lower than in the Runx2-negative group." (PMID 28264434, 2017). "The Runx2 and its co-activator CBF-β regulates expression of matrix proteins and metalloproteinases (MMP9 and MMP13), osteocalcin, bone sialoprotein and genes related to cancer cell migration and invasion." (PMID 24479521, 2014). "Also at cytoband 6p21.1 is the human cyclin D3 gene CCND3, which is commonly amplified in other cancers, CDC5L (cell division cycle 5-like), and RUNX2 (runt-related transcription factor 2)." (PMID 22685381, 2012). "Runx2 is also a major target gene of TGFβ /BMP signaling pathway and the interaction between Runx2 and Smads results in regulation of downstream target genes in osteoblasts, chondrocytes and cancer cells." (PMID 22537242, 2012). "The up-regulation and down-regulation of genes in the cancer cells could also be attributed to the activation of specific transcription factors such as ATF3, RUNX2, ERG, DLX1 (and DLX2) identified in the cancer cell transcriptomes." (PMID 20021671, 2009). "Notably, RUNX2 enhances HIF-1α-mediated VEGF induction, and recent studies suggest that RUNX2 may also contribute to drug resistance in malignant tumours." (PMID 40806771, 2025). "Additionally, RUNX2 and PI3K/AKT form a positive feedback loop that stimulates MMPs, VEGF, bone matrix proteins, bone-resorbing factors, and other genes related to invasion and metastasis, thus assisting in reprogramming cancer cells to undergo EMT." (PMID 40806771, 2025). "Interestingly, the difference in the percentage of CD8+RUNX2+T among CD8+T cells between cancer or paracancer tissues was not statistically significant." (PMID 39822248, 2024). "However, despite increasing evidence of the importance of RUNX2 in various cancers, there are no reports about its relevance in CC." (PMID 33365318, 2020). "Considering that RUNX2 induces osteogenic genes expression through the RUNT DNA binding domain, we hypothesized that the RUNT domain might also be responsible for the bone tropism of cancer." (PMID 32204402, 2020). "Therefore, RUNX2 and CD44-ICD are potential targets for anti-cancer therapy, and attenuation of their interaction may validate the regulatory effects of these proteins on cancer migration and progression." (PMID 31331331, 2019).
cancer (continued). "In addition, the cancer cell-derived osteoclast-activating factors MCSF, IL-6, IL-8, RANKL, MMP2, MMP13, RUNX2 and PTHrP are significantly down-regulated in MDA-MB-231 cells transfected with miR-124 mimic and up-regulated in MCF7 cells transfected with miR-124 inhibitor." (PMID 29343249, 2018). "Additionally, a MiR-23a/RUNX2/VEGF-A pathway was identified in endothelial cells, and this may provide new strategy for cancer therapy." (PMID 28938538, 2017). "Therefore, in most BC cell lines, the anti-cancer activity of CADD522 could be, in part, through its targeting of RUNX2-DNA binding." (PMID 29050333, 2017). "Therefore, therapy agents such as roxithromycin, which has inhibited RUNX2 and PTHLH expression, might prevent the HNSCC proliferation and other PTHLH induced cancer related complications." (PMID 28120940, 2017). "Because SNAI2 has been implicated in EMT and in the invasive metastatic behavior of breast and other cancer cells we employed the MCF7/Rx2dox culture system to test the hypotheses that Runx2 induces and E2 antagonizes EMT and invasiveness, and that SNAI2 plays a role in these processes." (PMID 22151997, 2011). "Comparison of these two cell types may reveal the biological purpose of the aberrant ectopic expression of RUNX2 in non-osteoblastic cancer cells." (PMID 21029421, 2010). "Our studies support the general concept derived from multiple studies that RUNX2 may function as a metastasis-related oncoprotein in non-osseous cancer cells." (PMID 21029421, 2010). "On the other hand, the wide range of Runx2 mRNA expression in PDAC and CP reflects the heterogeneous composition of these tissues, especially of the Runx2 overexpressing tissue elements such as tubular complexes, PanIN lesions, and cancer cells (in PDAC tissues)." (PMID 17876328, 2007). "For the positive–negative subjects (screening), 3 CNAs were detected in BC genes (ACVR2A, CUL3 and PIK3R1), and 5 SNPs were identified in 6 non-BC cancer genes (SNIP1, TBC1D10B, PANK1, PRKCA and RUNX2; SUPT3H)." (PMID 35589867, 2022). "Using PPI analysis, the critical pathway of functional genes was found involved in the hematopoietic cell lineage and transcriptional misregulation in cancer, including HOXA10, MEIS1, FLT3, CD14, PROM1, RUNX2, and RUNX1 (data not shown), indicating the dominant roles of HOXA and MEIS1 in MLL-R ALL." (PMID 36276286, 2022). "Whether the cooperative interaction of RUNX2 with HDACs contributed to the alternative splicing of OPN, especially in cancer cells following TGF-β induction, was not known to date." (PMID 31832019, 2019). "In addition, this is the first study showing the effects of this binding domain on genes involved in cancer, such as STMN1 or SSBP1, which are not direct targets of RUNX2." (PMID 30463392, 2018).
infection (41 papers, 2006 to 2025). The state of being infected such as from the introduction of a foreign agent such as serum, vaccine, antigenic substance or organism. "The expression of the recognized early osteogenic marker RUNX2 was measured on Days 1 and 2 after infection." (PMID 36698376, 2023). "In this study, an early increase in the osteoblastic precursor RUNX2 mRNA was detected at 3 days post infection in Nav1.8-DTA mice." (PMID 35639178, 2022). "MicroRNA-23b was also reported as an endogenous attenuator of RUNX2 in BMSCs, and infection with Ad-RUNX2 (adenovirus carrying the entire coding sequence of RUNX2) effectively rescued the suppression of osteogenesis in microRNA-23b-overexpressing BMSCs." (PMID 34281266, 2021). "After infection with a RUNX2 short‐hairpin RNA (shRNA) lentiviral vector (knockdown), RUNX2 expression was downregulated compared with that of the scrambled shRNA lentiviral vector (knockdown control, K‐control) group." (PMID 31830314, 2020). "Briefly, MSCs (C3H10T1/2) infected with adenovirus expression H19 were cultured in micromass; 3 days after infection, cells were lysed and mixed with anti-Runx2 tagged beads." (PMID 32903671, 2020). "When iMADs cells were infected with Ad-BMP9, osteogenic regulator Runx2 expression was significantly up-regulated at 36, 72 and 96 hours after infection, while Runx2 downstream target Osx was up-regulated at 96h time point." (PMID 31825894, 2019). "We found that the modified virus improved the survival of the well-characterized MYC/Runx2 mouse compared to infections with the wild-type MLV." (PMID 31815961, 2019). "Infection with type II Runx2-expressing adenovirus induced Fgfr1, Fgfr2, and Fgfr3 mRNA and their IIIb and IIIc isoform mRNA." (PMID 30202094, 2018). "The infection efficiency of Ad-Runx2 in ADSCs was 99.69%, as indicated by flow cytometric detection of the EGFP marker 48 h post-infection." (PMID 26743583, 2016). "The infection of Runx2-expressing adenovirus into Runx2−/− calvarial cells upregulated Sp7 expression 10 times after 6 hours and 50 times after 12–48 hours compared with that before infection." (PMID 22396760, 2012). "Runx2 expression levels were significantly increased in WT and KO cells following infection with a Runx2 adenovirus relative to control adenovirus." (PMID 21559363, 2011). "Ad-Cre infection in primary osteoblasts isolated from the β-cateninfx/fx mice inhibited Osthole-induced expression of Runx2, ALP, and BSP, as well as Bmp2." (PMID 20200936, 2010). "Nevertheless, it is tempting to speculate that Gata3 and Runx2 may combine to help shape CD8+ T cell responses to infection." (PMID 40012375, 2025). "Our results indicated that the RUNX2 gene mRNA level fluctuated throughout the differentiation process, with significant decreases observed at 7 and 21 days post-infection but recovery at 14 days post-infection." (PMID 39338991, 2024). "BM-MSCs infection by ZIKV causes increased IL-6 expression and impaired osteoblast differentiation, pointed out by a decreased expression of alkaline phosphatase (ALP) and Runt-related transcription factor 2 (RUNX2)." (PMID 35887383, 2022). "However, it is important to highlight that the results of qPCR assays showed a decrease of their mRNA expression after infection with sh-RUNX2." (PMID 36510562, 2022). "Indeed, Bmp2 and Runx2 synergistically induced Smoc1 and Smoc2 expressions as an early response to infection." (PMID 34667264, 2021). "Consistently, infection with Mtb activated BMP/SMAD/RUNX2 signaling pathway in BMDMs, which effect could be inhibited by LDN-193189." (PMID 33097805, 2020). "We also demonstrate that infection inhibited gene expression of RUNX2." (PMID 32493723, 2020). "Infection of MYC/Runx2 mice with WT MLV reduced animal survival by 10 days." (PMID 31815961, 2019). "The results revealed no significant change in the osteogenic capability within 24 h, but a significant decrease in the osteogenic genes RUNX2, OCN and ALP was observed after 7 days of infection." (PMID 40889211, 2025).
infection (continued). "In vitro experiments, we found that butyrate significantly enhanced the expression of osteogenic‐related genes down‐regulated by infection in MC3T3‐E1 cells induced by S. aureus, including RUNX2, OCN, and ALP." (PMID 40889211, 2025). "A significant reduction of ALP and RUNX2 expression was observed in ZIKV-infected differentiating osteoblasts compared to uninfected controls (p value < 0.05) at day 7 post-infection." (PMID 30451958, 2018). "Infection with IGF1 (ADIGF1) significantly increased ALP activity and mRNA expression levels of Runx2 and OPN compared to infection with control recombinant adenoviruses (ADGFP)." (PMID 28387248, 2017). "Infection of IFT80f/f and IFT80d/d OPCs with Ad-BMP2 or Ad-Runx2 significantly promoted BMP2 or Runx2 expression." (PMID 26996322, 2016). "Western blot and qRT-PCR analyses indicated that the expression of COL1, ALP, RUNX2, and OCN was significantly increased by miR-29b-3p mimic infection, while these osteogenic transcription factors and markers were downregulated after transfection with miR-29b-3p inhibitors." (PMID 37010483, 2023). "On the other hand, proapoptotic proteins BAD and BAX have not shown changes in their protein expression after infection with sh-RUNX2." (PMID 36510562, 2022). "We found promising master regulators of duck genes in lung and ileum (RUNX2, SMAD3, SMAD4, and ETS1), which could be responsible for the duck’s effective differential gene expression in response to HPAI infection." (PMID 35205087, 2022). "Globally, the infection time course for the IN TP- series showed a biphasic DoD curve, with one-third of the mice developing tumors early, as with WT infection, and two-thirds of the mice developing tumors later, paralleling the uninfected MYC/Runx2 control mice." (PMID 31815961, 2019). "Using real-time RT-PCR, Runx2 mRNA was detected in ADSCs infected with Ad-Runx2 at 1, 3, 7, 10 and 14 days post-infection, but not in Ad-EGFP-infected ADSCs." (PMID 26743583, 2016). "Ciglitazone at a concentration of 5 μMdecreased the T3-induced expression of Runx2 by 36%.Ad-PPARγ infection decreased the expression of Runx2 mRNAby 54% in the absence of ciglitazone and by 66% in thepresence of 5 μM of ciglitazone." (PMID 17259668, 2006). "In our in vitro model of osteoblast lineage infection, we first observed that internalized S. aureus 8325-4 (a reference lab strain) significantly impacted RUNX2 and COL1A1 expression compared to its non-internalized counterpart 8325-4∆fnbAB (with deletion of fnbA and fnbB)." (PMID 34480054, 2021). "While infection did not cause a cytopathic effect, a significant reduction of key osteogenic markers such as ALP, RUNX2, calcium contents and increased expression of IL6 in ZIKV-infected MSCs implicated a delay in osteoblast development and maturation, as compared to uninfected controls." (PMID 30451958, 2018).
skeletal disease (14 papers, 2011 to 2025). "In particular, we reported that in patients affected by CCD, an autosomal dominant inherited skeletal disease, RUNX2 mutations impair osteogenic differentiation." (PMID 35652047, 2022). "Targeting the CK2/USP7/RUNX2 axis presents a potential therapeutic strategy for managing CKD-related bone disorders." (PMID 40447997, 2025). "Skeletal diseases emphasize the significance of Runx2 activity during human osteogenesis, and Runx2 is also necessary for osteogenic differentiation." (PMID 38515940, 2024). "In this review, I summarize the emerging RUNX2-mediated regulatory mechanism from a multi-layer perspective and discuss future perspectives for applications in the treatment of skeletal diseases." (PMID 36769300, 2023). "Mutation and dysregulation of RUNX2 is a key factor giving rise to human CCD, an autosomal-dominant skeletal disease that is typically characterized by delayed closure of calvarial fontanels and clavicle hypoplasia." (PMID 35953487, 2022). "It is interesting to note that in the ChIP experiments detecting acetylation levels at Runx2, patients with pre-existing skeletal disease (MM2, 3) responded better to XRK2F2 treatment than the ones without a skeletal disease diagnosis (MM1, 4)." (PMID 30008697, 2018). "Further characterization of this Runx2-Col10a1 interaction has the potential to identify novel therapeutic targets for multiple skeletal diseases showing altered Col10a1 expression and chondrocyte maturation." (PMID 21887706, 2011). "Since RUNX2 represents a key player of bone metastatic process, the detection of RUNX2-targeting microRNAs in the blood could be extremely useful to monitor and control skeletal disease progression." (PMID 32582538, 2020). "In mammals, three RUNX members, namely RUNX1, RUNX2, and RUNX3, play distinct and redundant roles, although RUNX2 is a dominant factor in skeletal development and several skeletal diseases." (PMID 37436583, 2023).
skeletal dysplasia (12 papers, 2016 to 2026). Any Mendelian diseases that affects growth and development of the skeleton. "A cause of this skeletal dysplasia is heterozygous mutations of the runt-related transcription factor 2 gene (Runx2), a master regulator for bone and cartilage development." (PMID 33747589, 2021). "The absence of posterior HOX9, HOX11, and HOX13, which are associated with limb development and hypertrophic RUNX2/3 expression, may be at least partially responsible for the improper development in skeletal dysplasias." (PMID 36810131, 2023). "Our study demonstrated that the Mediator subunit MED23 acts as a cofactor of RUNX2 in the regulation of osteoblast differentiation and bone development, providing an insight into the regulation of RUNX2 activity and skeletal dysplasias such as CCD." (PMID 27033977, 2016). "HDAC6 has been shown to interact with Runx2, a transcription factor involved in osteoblast differentiation, and other HDACs exhibit high expression patterns in prehypertrophic chondrocytes, indicating their role in endochondral ossification and skeletal dysplasias." (PMID 38439105, 2024). "Conversely, inhibitors or insufficient transactivators may decrease Col10a1 expression and delay chondrocyte maturation and thus contribute to low bone growth as seen in skeletal dysplasia, or less cartilage degradation as seen in Runx2+/− mice of an OA mouse model." (PMID 34276786, 2021).
genetic diseases (9 papers, 2011 to 2025). "RUNX2 is also associated with genetic diseases such as congenital osteogenesis defects, with RUNX2 deficiency being the cause of acromioclavicular dysplasia syndrome." (PMID 41041663, 2025). "In addition, this epigenetic approach has the potential to treat certain genetic disorders such as cleidocranial dysplasia caused by mutations in Runx2." (PMID 32796747, 2020). "For example, dysplasia disease is a genetic disorder of abnormal cellular development due to imperfect polyalanine expansions (GCC repeats) on RUNX2 (CBFA1)." (PMID 24800246, 2014).
cardiovascular diseases (8 papers, 2014 to 2025). "In this study we investigated the expression of osteocalcin (OC), osteopontin (OPN) and RUNX2 in patients’ leukocytes and their possible role as diagnostic markers for cardiovascular diseases." (PMID 33809272, 2021). "In our present investigation we studied the expression of OC, OPN and RUNX2 in patients’ leucocytes and their possible role as diagnostic markers for cardiovascular disease." (PMID 33809272, 2021). "Vascular calcification is a hallmark of advanced cardiovascular disease, caused by VSMC phenotypic switching from a contractile to an osteogenic state marked by RUNX2, MSX2, and ALP expression." (PMID 41189994, 2025). "The intricate crosstalk among the Notch signaling pathway, BMP2 and RUNX2 playsa pivotal role in the pathogenesis of cardiac fibrosis, influencing theprogression and outcomes of cardiovascular diseases." (PMID 39484128, 2024). "In summary, the protein–protein interaction data and our in vivo reporter system has led us to identify FHL2 as a promising candidate for regulating RUNX2 activity in vascular smooth muscles and potential therapeutic target for cardiovascular diseases." (PMID 38664060, 2024). "In cardiovascular diseases, pathological expression of Runx2 results in vascular calcification by promoting differentiation of macrophages into osteoclast-like cells." (PMID 36198906, 2022). "In cardiovascular diseases, the pathological roles of Runx2 have been reported." (PMID 36198906, 2022). "Of note, while non-calcified valves were free of visible signs of calcification, and patients had no clinical history of cardiovascular disease, some expression of RUNX2 was observed in these samples." (PMID 33057457, 2020).
adenocarcinoma (4 papers, 2013 to 2026). A common cancer characterized by the presence of malignant glandular cells. "Here, we report for the first time in TRAMP mice, dynamic expression changes of the transcription factors, Runx1 and Runx2, and microRNAs that contribute to deregulated expression of Runx proteins, during the transition of normal prostate tissue to adenocarcinoma." (PMID 27634876, 2016).